HSF1 (heat shock transcription factor 1)
Diseases named in the same sentence as HSF1 in open-access papers (continued):
Sharing a sentence is not in itself a finding about the gene and the disease.
infection (33 papers, 2005 to 2025). The state of being infected such as from the introduction of a foreign agent such as serum, vaccine, antigenic substance or organism. "In the worm, infection is a major cause of death, detectable by pharyngeal swelling, and hsf-1 knockdown increases pharynx bacterial colonization." (PMID 36490338, 2022). "HSF1 is essential for the optimal immune response against various pathogenic infections in both C. elegans and animal models." (PMID 34239690, 2021). "It appears that different contexts (infection, heat-shock, or mutations) result in either pro-inflammatory or anti-inflammatory effects of HSF1." (PMID 33288768, 2020). "The expression of HSF1 in both susceptible and resistant plants following Foc1 infection suggests its common regulatory mechanism to prevail in both systems which is probably linked more to pathogen attack than to regulating defense response." (PMID 28542579, 2017). "This view is supported by the findings that (i) the infection phenotype of lin-7 mutants was suppressed when treated with hsf-1 dsRNA, and (ii) loss of lin-7 resulted in a significant delay in DAF-16::GFP nuclear localization." (PMID 22672310, 2012). "These prior observations and the finding that loss of hsf-1 activity suppressed the infection phenotype of lin-7 mutants led us to investigate whether lin-7 deficiency would also affect the kinetics of DAF-16 nuclear localization." (PMID 22672310, 2012). "However, it still remains unclear whether the HSF-1 pathway regulates a constitutive innate immunity or is only activated upon stresses caused by pathogen infection." (PMID 25062095, 2014). "HSF1 has been identified as a key host factor for the successful completion of the infection cycle of orthopoxviruses, for example, the viruses that cause monkeypox and smallpox." (PMID 40457168, 2025). "At the molecular scale, heat‐shock transcription factor 1 (HSF‐1) and its downstream targets increase host survival when challenged by thermal stress, infection and the effects of aging (Hsu, Murphy, and Kenyon 2003; Singh and Aballay 2006)." (PMID 39529601, 2025). "Altogether, these results indicate that general stress response pathways governed by DAF-16, SKN-1, and HSF-1 actively participate in the physiological response to infection." (PMID 39000143, 2024). "HSF-1 detects misfolded, denatured proteins in response to proteotoxic insults, such as heat shock and oxidative stress during infection." (PMID 39000143, 2024). "In contrast, the Hsf1 accessory copies of these two strains were under opposite regulations, with Fo47 one being up-regulated and Fo5176 one being down-regulated post infection, suggesting distinct regulatory adaptations after expansion." (PMID 36798233, 2023). "On the other hand, the increased proliferation rate observed in Hek293 cells at longer times of infection was strictly dependent on HSF1 activation and downstream synthesis of Hsp27." (PMID 34845419, 2021). "To investigate the change in HSF1 expression during the conidia infection process, we assessed the mRNA levels of HSF1 in A. fumigatus conidia-infected cells." (PMID 34204112, 2021). "The budding yeast and occasional human pathogen Candida albicans similarly requires a temperature increase to trigger the bud-to-hyphae transition critical for infection, which also induces chaperones in a classical Hsf1-mediated heat shock response." (PMID 32762843, 2020). "The protein folding stress response system is regulated by the transcription factor HSF-1, whose inactivation has been shown to render worms sensitive to infection." (PMID 31771413, 2019). "To determine if phosphorylated HSF1 is relocating to the nucleus upon infection, we undertook immunofluorescence analysis of HSF1." (PMID 24516381, 2014). "Our results demonstrating a role for HSF1 in vaccinia replication suggested that HSF1 was being activated following infection." (PMID 24516381, 2014).
infection (continued). "To investigate the possible contribution of HSF-1 towards the enhanced survival exhibited by lin-7 mutants during infection, we compared the infection outcomes of wild-type nematodes and lin-7 mutants in the presence or absence of hsf-1 dsRNA." (PMID 22672310, 2012). "The finding that inhibition of hsf-1 suppressed the infection phenotype exhibited by lin-7 mutants suggested that in addition to DAF-16, HSF-1 also plays a significant role in the ability of LIN-7 to modulate host infection outcomes." (PMID 22672310, 2012). "HSF1 is a transcription factor that activates gene expression in response to several types of stress, including heat shock, oxidative stress, inflammation, and infection." (PMID 40497989, 2025). "Furthermore, a significant enhancement of the binding of HSF1 to the HIV LTR was observed upon HSV-∆ICP34.5 infection, leading to an increase in the reactivation of HIV latency." (PMID 40266253, 2025). "Future studies aiming at the systematic depletion of different HSF1-target genes will be crucial for identifying the specific molecular chaperones and/or pro-survival HSPs that are co-opted by human coronaviruses within the host cell during infection." (PMID 39243335, 2024). "We found that mutations in skn-1, daf-16, hlh-30, zip-2, or hsf-1 partially suppressed the increased survival of aco-2 RNAi-treated animals upon PA14 infection, or had nonspecific effects." (PMID 37349299, 2023). "Given that virus‐infected cells may undergo some level of UPR due to sustained viral protein translation during infection, it is also possible that a link may exist between this response and HSF1." (PMID 35485710, 2022). "To test whether tbb-6 might be part of an immune response separate from the UPRmt, we assayed Ptbb-6::GFP expression in isp-1(qm150) worms upon RNAi knockdown of four genes reported to mount cellular defenses against infection: elt-2, fshr-1, hsf-1 and zip-2." (PMID 27420916, 2016). "However, at later times in infection, levels of phosphorylated HSF1 strongly increased, similar to that seen following heat-shock." (PMID 24516381, 2014). "Orthopoxviruses may need HSF1 directly or may activate its transcriptional activity to enhance production of an HSF1-regulated target that is necessary for infection." (PMID 24516381, 2014). "More inhibition of late gene expression was observed compared to early gene expression; this may be due to the cascade transcription mechanism employed by poxviruses or HSF1 may be more important for late stages of infection than early." (PMID 24516381, 2014). "The present findings showed that after PA14 infection, the mRNA levels of selected immune-related genes (namely, irg-1, hsf-1, lys-1, spp-1, and abf-1) (Ctrl + PA14) were significantly suppressed 20% to 80% compared with that of the uninfected group (Ctrl + OP50) without Se(IV) treatment." (PMID 25147937, 2014). "Genetic and biochemical experiments revealed that lin-7 modulates the DAF-2 insulin/IGF-1 signalling pathway, by binding directly to the DAF-2 RTK via LIN-2, and that both daf-16 and hsf-1 are required for the enhanced survival exhibited by lin-7 mutants upon infection." (PMID 22672310, 2012). "However, biphasic kinetics of HSF1 mRNA is observed after high dose infection (5 pfu/cell) with the minimum at 6 to 24 h p.i. corresponding to the maximal viral gene transcription." (PMID 16246258, 2005). "However, after infection of AdSmad3, these markers were significantly upregulated by mechanical stretch, indicating that inhibition of Smad3 is the key mechanism mediating the HSF1-induced anti-fibrotic effect." (PMID 28091697, 2017). "Interestingly, heat shock factor-1 (HSF-1) is also upregulated during this stage of infection." (PMID 29295496, 2017). "When HSF1 is depleted from the cell, the cellular milieu may be altered such that it is non-permissive for orthopoxvirus infection, or alternatively the virus may directly require active HSF1 transcription during infection." (PMID 24516381, 2014).
infection (continued). "In our study, the abundance of HSF1 was significantly higher in SHIV-Exo than in CTL-Exo, possibly promoting productive infection and deleterious neuroinflammation in CNS." (PMID 36992502, 2023). "Of note, we demonstrated that si‐Hsf1 counteracted melatonin‐mediated suppressive effects on the levels of IL‐1β and TNF‐α in the serum and lung at 12 h post PmCQ2 infection." (PMID 35184395, 2022). "Prior to each infection, we split a population of MDCKHSF1 cells and treated with TMP to activate HSF1, STA-9090 to inhibit Hsp90, or vehicle." (PMID 28949290, 2017). "More recently, olfactory stimulus by P. aeruginosa-related cues has been proven to enhance HSF-1-mediated expression of chaperones, as well as the aversion of PA14 lawn upon a secondary infection, showing a neuroendocrine priming of HSF-1-dependent antimicrobial defenses." (PMID 39000143, 2024). "Thus, the role of HSF1 in HIV infection is yet to be fully elucidated, as altogether there seem to exist some paradoxical effects for HSF1 during infection with this virus." (PMID 35485710, 2022). "Similarly, Ad‐FAM3C infection also up‐regulated the expression levels of YY1 and HSF1 mRNAs and proteins with Akt activation when compared with Ad‐GFP–treated cells." (PMID 30887707, 2019). "Basal levels of HSF1 phosphorylation are seen in VACV-infected cells at 30 minutes post infection (lane 3) suggesting that there is no immediate change in HSF1 activation during virus entry." (PMID 24516381, 2014). "Although the exact interaction between the insulin signalling pathway and HSF-1 during infection is not yet well characterized, recently, this interplay has been dissected in the context of ageing." (PMID 22672310, 2012). "On the other hand, the decrease in HSF1 mRNA observed at the beginning of the infection does not severely affect the protein content because of a fairly long half life time of HSF1 protein." (PMID 16246258, 2005). "For example, HSP90/HSF1-driving LRAs may theoretically show differential efficacy against HIV-1 versus HIV-2; however, this has not been experimentally demonstrated and requires explicit testing in dual-infection systems." (PMID 41416109, 2025). "Likewise, HSF-1 and DAF-16 collaborate to protect proteostasis during PA14 infection." (PMID 39000143, 2024). "Using silencing experiments and a direct HSF1 small-molecule inhibitor we show that, intriguingly, HCoV-mediated activation of the HSF1-pathway, rather than representing a host defense response to infection, is hijacked by the pathogen and is essential for efficient progeny particles production." (PMID 39243335, 2024). "Validation of the gene expression levels obtained by RNA-seq specific to the HCV group (BIRC5 and SLC22A1), the HBV group (CLEC1B), and the group without infection (FGFR4, HSF1, RNF187, HSP90AB1, and HSPB1) was performed using the real-time PCR technique." (PMID 36557005, 2022).
metabolic disorders (8 papers, 2012 to 2025). "The role of HSF1/Hsp in metabolic disorders-induced vascular inflammation and injury remains to be further investigated but appears to be both pro- and anti-inflammatory." (PMID 23304460, 2012). "The HSF1/Hsp-mediated stress response to exercise and metabolic disorders play, distinguishable and possibly opposite roles in vascular inflammation, which may be related to the involvement of different types of Hsp, body temperature, or shear stress of blood flow." (PMID 23304460, 2012). "Moreover, it should be noted that the disturbed cross-regulation loop between HSF1 and FAM3A pathways might play vital roles in the development of metabolic disorders." (PMID 38937853, 2024).
bacterial infection (7 papers, 2012 to 2024). "Likewise, an important aging-associated phenomenon is immune failure and bacterial infection, which is enhanced in hsf-1, daf-16, skn-1 and also in daf-21 nematodes." (PMID 30104664, 2018). "For instance, HSF1 is known to initiate host defense against bacterial infection, partly through promoting early TLR2 signaling activation." (PMID 34944618, 2021). "Furthermore, studies have suggested that HSF1 is required to initiate the host defense against bacterial infection through early activation of TLR2 signaling." (PMID 37893128, 2023). "In addition to DAF-16, HSF-1 is required for the enhanced survival of daf-2 mutants during bacterial infection." (PMID 22672310, 2012). "Among the genes regulated by HSF-1 are molecular chaperones of the heat-shock protein family (HSPs) that may indirectly add to the innate immune response by supporting the refolding of unfolded proteins resulting from the release of ROS as a measure to fight the bacterial infection." (PMID 27138431, 2016).
adenocarcinoma (3 papers, 2019 to 2023). A common cancer characterized by the presence of malignant glandular cells. "Since HSF1 is known to regulate the ageing process, we tested whether its target genes in any of the three cell types (adenocarcinoma, erythrocarcinoma, and breast epithelium) are associated with longevity." (PMID 31752429, 2019). "In CRPC and NEPC, HSF1 expression was also highly amplified, with more accumulation of HSF1 than in adenocarcinoma and benign tumors." (PMID 37958341, 2023).
neurological disorders (3 papers, 2016 to 2023). "Several neurological disorders are caused by accumulation of misfolded proteins typically associated with the loss of HSF1 function and/or low activity of chaperones." (PMID 36610605, 2023). "Our research expands upon these functions, potentially implicating HSF-1 and small HSPs as a central intracellular hub linking genetic predisposition to multiple, complex neurological disorders, including susceptibility to addiction." (PMID 26773049, 2016). "In mammals, for instance, the inhibition or elevation of Hsf1 results in the development of neurological disorders and cancer, respectively." (PMID 37168390, 2023). "Mammalian Hsf1 activator and inhibitor have demonstrated efficacy in the treatment of mammalian ailments, such as neurological disorders and malignancies." (PMID 37168390, 2023).
benign tumors (2 papers, 2018 to 2023). "Among transcription factors regulating chaperones, the enhancement of heat shock transcription factor 1 (HSF-1), but not the HSF-2 activity has been described after cardiac I/R in post-ischemic rat heart." (PMID 29615920, 2018).
cardiovascular disease (2 papers, 2019 to 2023). "HSF1 and HSPs confer protection against cardiovascular diseases, including atrial fibrillation, cardiac hypertrophy, and cardiomyopathy." (PMID 37077734, 2023). "HSF1 performs very important functions in cardiovascular disease." (PMID 31627188, 2019).
heart disease (2 papers, 2019 to 2020). "HSF1 is a critical transcriptional factor correlated with chronic stresses and heart disease." (PMID 31627188, 2019). "Previous research demonstrated that both HSF1 and ALDH2 are critical endogenous protective factors of the heart and play an important protective role in heart diseases." (PMID 32626739, 2020).
hematological malignancies (2 papers, 2022 to 2023). "In hematological malignancies, the role of HSF1 has also been partially explored." (PMID 36069792, 2022). "Very few studies have explored these non-classical functions of HSF1 in hematological malignancies." (PMID 36765939, 2023).
kidney diseases (1 paper, 2023). "Therefore, it will be interesting to explore whether the HSF1-SSBP1 complex modulates ferroptosis and kidney diseases and to identify new targets of HSF1 that may be closely associated with ferroptosis." (PMID 37739961, 2023).
retinopathy (1 paper, 2019). "This study highlights the potential value of boosting endogenous protective mechanisms including HSF1 activation for treating retinopathy." (PMID 30884523, 2019).
HSF1 also shares sentences with these, for which no sentence is quoted: head and neck squamous cell carcinoma (3 papers); Parkinson’s (3); carcinoma in situ (2); gynecologic cancer (2); hypertrophy (2); Myocardial fibrosis (2); adrenocortical carcinoma (1); airway hyperresponsiveness (1); anemia (1); aortic valvular stenosis (1); aspergillosis (1); asthenozoospermia (1); Ataxia (1); attention deficit-hyperactivity disorder (1); autoimmune disease (1); bipolar disorder (1); bone cancer (1); brain injury (1); cataract (1); cervical adenocarcinoma (1); cervical squamous cell carcinoma (1); cholestasis (1); chronic myeloid leukemia (1); chronic pancreatitis (1); Cirrhosis (1); clear renal cell carcinoma (1); diffuse Lewy body disease (1); embryonic carcinoma (1); endocervical adenocarcinoma (1); Fanconi's anaemia (1).
A further 49 diseases each share a sentence with HSF1 in 1 paper.